RNU6-1013P (RNA, U6 small nuclear 1013, pseudogene)
Gene: Small nuclear RNA gene on chromosome 9 (111,839,828 to 111,839,934, forward strand). Ensembl gene ENSG00000206907.
Homologues: Orthologues: chimpanzee U6 (100% identical), macaque U6 (94% identical). Paralogues in human: RNU6-15P (90% identical), RNU6-188P (90% identical), RNU6-17P (89% identical), RNU6-18P (89% identical), RNU6-224P (89% identical), RNU6-266P (89% identical), RNU6-71P (89% identical), RNU6-1 (88% identical), RNU6-1005P (88% identical), RNU6-1011P (88% identical), RNU6-12P (88% identical), RNU6-13P (88% identical), and 1285 more.